IL6 (interleukin 6)
Diseases named in the same sentence as IL6 in open-access papers (continued):
Sharing a sentence is not in itself a finding about the gene and the disease.
type 2 diabetes (continued). "Obese women with type 2 diabetes (T2D) and chronic inflammatory diseases are at higher risk of breast cancer, asT2D with obesity mediates the production of IL6, IL7, and CD68 macrophages, such as proinflammatory cytokines, which exacerbate the invasion of metastatic cancerous cells." (PMID 35401196, 2022). "Moreover, it has been found that low-grade inflammation predicts incident type 2 diabetes, with the inflammatory marker IL-6 driving this association." (PMID 34932135, 2022). "Also, leptin upregulates proinflammatory cytokines such as interleukin 6, which is associated with dyslipidemias, IR, and type 2 diabetes." (PMID 35386232, 2022). "Besides, patients with type 2 diabetes have a higher level of anti-HSP60 antibody in association with C-174G polymorphism in the promoter region of the IL-6 gene." (PMID 34239605, 2021). "Data from a meta-analysis reveals that T2DM (type 2 diabetes mellitus) risk as a whole was solidly correlated with increased levels of inflammatory cytokines such as interleukin (IL) 1β, IL-6, IL-18, C reactive protein (CRP) and tumor necrosis factor-α (TNF-α)." (PMID 34829612, 2021). "Indirect evidence, however, comes from the Whitehall II Study (n = 4638; 39–63 years), which assessed the association between psychosocial stress (as a potential cause for the cortisol secretion pattern) and type 2 diabetes and confirmed that this association was weakly mediated by IL-6." (PMID 34206644, 2021). "In a study investigating the association of calcified coronary atherosclerosis and IL-6 in patients with type 2 diabetes, the level of IL-6 identified a significant association with the coronary arterial calcium score independent of other cardiovascular risk factors." (PMID 34071276, 2021). "The serum levels of superoxide dismutase, an antioxidant, was significantly increased, which was associated with decreased inflammation (hsCRP, TNF-α, IL-6) following 3 g/day taurine supplementation for 8 weeks (n = 50) in type-2 diabetic patients compared to control subjects." (PMID 32957558, 2020). "Epidemiological and clinical studies have shown that coffee consumption may reduce the levels of pro-inflammatory biomarkers such as interleukin(IL)-1b, IL-4, IL-6, IL-10, and C-reactive proteins, which can contribute to a reduced risk of type 2 diabetes." (PMID 32722593, 2020). "IL-6-597A/G and IL-6-174G/C are closely correlated with type 2 diabetes susceptibility." (PMID 31970102, 2019). "Similarly, elevated levels of circulating IL-6 can predict the incidence of type-2 diabetes in predisposed individuals." (PMID 30039349, 2019). "In addition to the effects of IL-6 on weight loss, Helga Ellingsgaard and colleagues report an acute increase in IL-6 improves glycemic in healthy and type 2 diabetic men by inhibiting gastric motility in a GLP-1-dependent manner." (PMID 31686269, 2019). "Epidemiological studies have reported that levels of pro-inflammatory and inflammatory cytokines such as C-reactive protein (CRP), TNF-α, IL-1β, and IL-6 were elevated in patients with type 2 diabetes and were associated with the development of type 2 diabetes." (PMID 30857216, 2019). "In PBMCs, the expression of genes encoding TNF-α and IL-6 was elevated in individuals with type 2 diabetes with micro- (n = 29) and macroalbuminuria (n = 31) compared with the control group (n = 22) and individuals with type 2 diabetes and normoalbuminuria (n = 18)." (PMID 29159468, 2018). "The variant role of family of IL6-genes has been studied in type 2 diabetes." (PMID 28179884, 2017). "In islets of spontaneous rat models of type 2 diabetes there was increased expression of Reg1 and Reg3 in association with peri-islet macrophage infiltration and release of various cytokines/chemokines, particularly IL-6." (PMID 26568772, 2015). "However, higher level of IL-6 is suggested to be associated with risk of coronary heart disease and type 2 diabetes." (PMID 24984610, 2014).
type 2 diabetes (continued). "Inflammation may also increase type 2 diabetes risk indirectly via obesity, which, as described, is a risk factor for type 2 diabetes and is associated with increased release of inflammatory markers, such as IL-6." (PMID 23843750, 2013). "Higher CRP and IL-6 concentrations were also associated with higher incidence of type 2 diabetes." (PMID 23843750, 2013). "We hypothesized that satellite cells derived from people with type 2 diabetes would demonstrate a deficient response to IL-6, which could contribute to the metabolic dysfunction of skeletal muscle in type 2 diabetes." (PMID 22761857, 2012). "However, the association of IL-6 and type 2 diabetes is not well understood to date, as several studies in rodents and humans have reported contradictory results." (PMID 21179199, 2010). "It has been suggested that association between IL-6 and progression to type 2 diabetes may reflect an attempt to counter-regulate the low-grade inflammation induced by other inflammatory mediators such as TNFα." (PMID 19936194, 2008). "Novel data have now appeared showing that the concomitant presence of the promoter polymorphisms of TNF-α and IL-6, linked to high production of these cytokines increases the risk of conversion to type 2 diabetes in obese subjects with impaired glucose tolerance response." (PMID 15904534, 2005). "A clinical study in men with type 2 diabetes who developed partial testosterone deficiency showed testosterone immunosuppressive activity in reducing the synthesis of the proinflammatory cytokines IL-1β, IL-6 and TNF-α, an effect that persists after termination of testosterone treatment." (PMID 36551196, 2022). "However, IL-6 may actually help to prevent or reduce risk factors associated with metabolic syndrome and type 2 diabetes in the long-term." (PMID 28555043, 2017). "Involvement of inflammatory markers such as IL-6 plasma levels and resistin in diabetic subjects confirmed the pathogenetic issue of the “adipovascular” axis that may contribute to cardiovascular risk in patients with type 2 diabetes." (PMID 25883983, 2015). "Our main findings in the present study were that the novel risk markers and tests IL-6, activin A, pathological recovery loop and E/Em all were significantly associated with a combined endpoint of CV events and mortality in a cohort of patients with type 2 diabetes at moderate CV risk." (PMID 23987834, 2013). "A prospective study suggested that IL-1β might interact with IL-6, participants with detectable IL-1β levels and elevated IL-6 levels presenting an increased risk to develop type 2 diabetes relative to individuals with undetectable IL-1β levels and increased IL-6 levels." (PMID 23251619, 2012). "In a previous meta-analysis of patients with type II diabetes who completed various forms of exercise training, IL-6 was reduced in the systemic circulation under resting conditions, indicating a potential reduction in chronic low-grade inflammation." (PMID 41562855, 2026). "For example, IL-6 levels are positively correlated with the severity of type 2 diabetes, and elevated IL-6 impairs tissue repair, leading to poor healing of diabetic foot ulcers." (PMID 40677522, 2025). "In a recent prospective cohort study of patients with type 2 diabetes, individuals with high periodontal inflammatory burden demonstrated significantly elevated serum IL-6 and CRP levels, which correlated with increased coronary artery calcification scores." (PMID 41007869, 2025). "For instance, probiotics and synbiotics have shown efficacy in lowering pro-inflammatory cytokines in prediabetes and type 2 diabetes, with a 2023 randomized trial demonstrating significant IL-6 and TNF-α reductions over 12 weeks." (PMID 41465826, 2025). "A reduction of IL-6 concentrations was found in the individuals with type 2 diabetes and heart failure after 3 months of treatment with empagliflozin." (PMID 40004134, 2025).
type 2 diabetes (continued). "Findings from two eligible studies in this systematic review portray conflicting perspectives regarding the role of IL-6 in type 2 diabetes and its complications." (PMID 41150802, 2025). "These mediators, which include C-reactive protein, interleukin-6 (IL-6), and TNF-α, raise the risk of developing chronic diseases like type 2 diabetes and cardiovascular disease." (PMID 40509530, 2025). "In particular, IL-6 levels are independently correlated with C-reactive protein (CRP) in adults with type II diabetes, indicating a link between inflammation and metabolic dysfunction." (PMID 41011276, 2025). "NF-κB drives the transcription of the inflammatory molecules TNF-α and IL-6, which facilitates the dysfunction in Type 2 Diabetes (T2D)." (PMID 40943351, 2025). "With these caveats in mind, interesting epidemiological studies have observed elevated circulating levels of IL-1β and IL-1-dependent CRP, IL-6 and IL-1Ra in individuals with type 2 diabetes." (PMID 39496966, 2025). "Another study showed that indoleacrylic acid (an indole derivative) alleviates type 2 diabetes by activating the aryl hydrocarbon receptor (AhR), which reduces IL-1β, IL-6, and TNF-α levels." (PMID 41156481, 2025). "Subjects with type 2 diabetes treated with SGLT2 inhibitors demonstrated lower plasma IL-6 levels compared to the patients treated with other antihyperglycemic agents." (PMID 40004134, 2025). "As elevated IL-6 is characteristic of delayed healing in type 2 diabetic patients, its downregulation supports the improved regenerative outcomes observed." (PMID 41394149, 2025). "BAT transplantation also protects against both type 1 diabetes by improving glycemia with increased IGF-1 and type 2 diabetes by improving glucose tolerance with increased IL-6 or adiponectin." (PMID 40362353, 2025). "One year of moderate-intensity combined with resistance training (MICT+RT) significantly lowered plasma IL-6 in type 2 diabetes patients." (PMID 40777031, 2025). "First, we complement existing evidence supporting an involvement of IL6 signaling in the pathophysiology of type 2 diabetes." (PMID 40858837, 2025). "In conclusion, elevated IL-18, NFATC4, TNF-α, and IL-6 levels suggest inflammation is key in prediabetes pathogenesis, highlighting the need for further research into interventions to delay or prevent type 2 diabetes." (PMID 40027364, 2024). "Hesperidin led to notable decreases in the levels of TNF-α and IL-6 in type 2 diabetes patients, while a hesperidin-derived metabolite suppressed endothelial cell inflammation." (PMID 39203784, 2024). "It was shown that regardless of the type of training, both in subjects with type 2 diabetes and in those from the control group, the levels of IL‐6 and IL‐8 were significantly reduced, and this effect was more visible in patients with type 2 diabetes." (PMID 38639648, 2024). "In one study, 500 mg of quercetin supplementation in women with type 2 diabetes led to a reduction in inflammatory markers TNF-α and IL-6, both of which are strongly associated with cardiovascular disease, indicating its potential benefits." (PMID 39539361, 2024). "In our study, the results revealed that serum IL-6 level in type II diabetes mellitus (T2DM) with peripheral arterial disease (PAD) patients was increased significantly (85.93) as compared to T2DM patients (59.52) and healthy individuals (4.81)." (PMID 38961103, 2024). "Patients with type 2 diabetes who were treated with Anakinra, Interleukin-1 receptor antagonist (IL-1Ra), for 13 weeks had reduced HbA1c, reduced systemic IL-6, IL-17, and C-reactive peptide, and an increased secretion of C-peptide." (PMID 39606781, 2024). "In contrast, the recombinant IC7Fc, which is constructed with consideration of tuning of the balance between the two primary IL-6 pathways, has exhibited multiple beneficial effects in the context of type 2 diabetes." (PMID 39749325, 2024).
type 2 diabetes (continued). "The goal of the research is to ascertain howTumour Necrosis Factor (TNFα), Type 2 diabetes has several etiopathogenic factors, including Interleukin-6 (IL-6), Interleukin-10(IL-10), and C - reactive protein (CRP)." (PMID 39132231, 2024). "Several other studies have investigated the relationship between inflammatory markers such as CRP and IL-6, and glycaemic traits and type 2 diabetes using MR, however, the results are inconsistent." (PMID 38730445, 2024). "Group B participants also exhibited a significant reduction in IL-6, consistent with findings in type 2 diabetes patients on maltodextrin supplementation." (PMID 39595910, 2024). "For example, she found that interleukin-6 (IL-6) plays a crucial role during muscle contraction, impacting the management and prevention of metabolic diseases such as type 2 diabetes." (PMID 39148743, 2024). "Plasma concentrations of hsCRP, IL-6, and leptin were higher in South Asians than in Nordics with normoglycaemia, but similar between the ethnicities in the prediabetes/type 2 diabetes group." (PMID 38786765, 2024). "The results of an investigation demonstrated astrong correlation between type 2 diabetics and TNFα, IL-6, CRP, and IL-10, receiving care at SMHS Hospital who is of Kashmiriorigin." (PMID 39132231, 2024). "We have previously reported that the balance between sIL-6R and sgp130, which form a buffer system to neutralize small amounts of systemic IL-6, is disturbed in type 2 diabetes patients." (PMID 39835136, 2024). "Canagliflozin has been shown to decrease serum leptin and IL-6 levels compared to glimepiride in patients with type 2 diabetes." (PMID 38566143, 2024). "White adipose tissues are a major source of inflammatory cytokines (e.g., TNFα, IL1, IL6, and others) and play a critical role in the development of type 2 diabetes." (PMID 37895942, 2023). "Proinflammatory leukins such as interleukin 6 (IL-6) are increased in patients with type 2 diabetes, and VD has been shown to reduce the production of several proinflammatory cytokines." (PMID 37569392, 2023). "In the remaining samples (healthy: 20; type 1 diabetes: 52; type 2 diabetes: 86), inflammatory cytokines were successfully measured in 99% (IL-6, TNF-α) and 100% (IL-8, IL-10, IFN-γ) of cases." (PMID 37189645, 2023). "We found that the expression levels of M1 polarized macrophage-related markers, including IL-1b, IL-6, and Tnf, were significantly enhanced in the peri-implantitis coupled with type II diabetes group." (PMID 37519314, 2023). "As conditions involving hyperactivation of the SNS such as type 2 diabetes (T2D) and hypertension display increased levels of IL-6 and its soluble IL-6 receptor (sIL-6R), we utilised the IL-6 and sIL-R fusion protein, hyper IL-6." (PMID 36979798, 2023). "This study found that CK treatment significantly reduced inflammatory factors, including TNF-α, IL-6, and IL-1β, in the liver injury model of type 2 diabetes rats." (PMID 37251340, 2023). "They observed different inflammatory stress response pathways in men and women with Type 2 diabetes, with women producing increased plasma IL-6 compared to men." (PMID 37545969, 2023). "In another study, empagliflozin and canagliflozin reduced circulating levels of IL-6 in men with type 2 diabetes." (PMID 36982786, 2023). "Liraglutide has been shown to decrease IL-6 in type 1 diabetic patients and hsCRP in patients with type 2 diabetes." (PMID 36982786, 2023). "In parallel with our findings, the meta-analysis reported that exercise significantly decreased inflammatory cytokine CRP and IL-6 in patients with type 2 diabetes after a brief period of exercise (12–14 weeks)." (PMID 38004306, 2023). "In type 2 diabetic patients, dendritic cells have been shown to accumulate in adipose tissue and promote the production of pro-inflammatory cytokines, such as IL-6 and TNF-α, by T cells." (PMID 38094119, 2023).
type 2 diabetes (continued). "IL-6 plays an important role in the pathogenesis of coronary artery disease as well as type 1 and type 2 diabetes." (PMID 36835557, 2023). "A longitudinal study following up for 10 years showed that higher levels of inflammatory markers such as serum interleukin-6 (IL-6) and C reactive proteins (CRP) were associated with subsequent cognitive decline in older adults with type 2 diabetes." (PMID 37213540, 2023). "C. papaya reinstated the levels of adipocytokines, antioxidant enzymes and mRNA levels of mTOR, TNF-α, IL-1β, IL-6 and IKKβ in the adipose tissues of type 2 diabetic rats." (PMID 36826001, 2023). "Studies have revealed that due to low-grade inflammation in obese and type 2 diabetic patients, the tissue and serum IL-6 levels are abnormally increased, which promotes the occurrence and development of chronic inflammation." (PMID 36376474, 2022). "For example, it was reported in the context of TB at the murine type 2 diabetes background that NK-CD11c+ cells were the main source of IL-6 at month 6 post challenge." (PMID 35154093, 2022). "We found that levels of IL-6 were significantly higher in the DN group as compared to the controls and with type 2 diabetes, also we observed that the levels of IL-6 in DN group were double the levels found in the diabetic group." (PMID 36363561, 2022). "In this 10 year follow-up of a representative cohort of older people with type 2 diabetes, higher baseline levels of systemic inflammatory markers, including plasma IL-6 and fibrinogen, predicted greater cognitive decline." (PMID 34932135, 2022). "Probiotics showed the potential to reduce the serum concentration of IL-6, TNF-α, and hs-CRP, which are the major risk factors for inflammation-dependent metabolic diseases like type-2 diabetes." (PMID 36211513, 2022). "Urinary excretion of renal tubular injury markers and inflammatory markers (such as IL-6) decreased in type 2 diabetes (T2DM) patients after treatment with dapagliflozin." (PMID 35351189, 2022). "To date, a variety of adipokines related to type 2 diabetes have been discovered and identified, including Adiponectin, Leptin, Visfatin, IL-6 and FGF21, etc." (PMID 35712241, 2022). "Previous studies have investigated that higher plasma IL-6 level is an independent marker for macrovascular events and mortality in type 2 diabetic patients." (PMID 36123740, 2022). "ELISA results showed that the expression of serum IL-6 was highest at 2 weeks after induction of type 2 diabetes, followed by a gradual decrease in expression compared with the non-diabetic group (p < 0.05)." (PMID 36299460, 2022). "The levels of IL-6 were significantly increased in the patients with type 2 diabetes, and diabetic nephropathy as compared to control individuals." (PMID 36363561, 2022). "In type 2 diabetes, elevated levels of serum pro-inflammatory cytokines such as IL-1β and IL-6 are predictive disease markers." (PMID 35399956, 2022). "Pro‐inflammatory cytokines, such as interleukin 6 (IL‐6), are known to sensitize peripheral nerve endings, and one study has suggested that IL‐6 level is increased by synovitis and the presence of type 2 diabetes in patients with knee OA." (PMID 35959735, 2022). "According to earlier reports, MCP-1 and IL-6 secreted from hUCMSCs can partially inhibit inflammation and induce polarization of M2 macrophages to restore islet function in type 2 diabetic mice." (PMID 36514009, 2022). "For example, vitamin E has been shown to reduce serum CRP and monocyte IL-6 levels in type 2 diabetic patients, and vitamin E has been shown to play a more important role than vitamin C in improving oxidant/antioxidant imbalance in HD patients." (PMID 35740095, 2022). "It has been suggested that IL-6 induces systemic chronic inflammation via its proinflammatory effects, which is central in the pathophysiology of type 2 diabetes." (PMID 36363561, 2022).